NR2F6 (nuclear receptor subfamily 2 group F member 6)
Diseases named in the same sentence as NR2F6 in open-access papers (continued):
Sharing a sentence is not in itself a finding about the gene and the disease.
Obesity (4 papers, 2020 to 2024). Accumulation of substantial excess body fat. "Our results showed that NR2F6 has a steatotic role in the development of obesity‐associated NAFLD and insulin resistance through direct upregulation of CD36 expression." (PMID 33173745, 2020). "Together, all of these results demonstrate that hepatocyte‐specific inhibition of NR2F6 can improve obesity‐associated liver steatosis." (PMID 33173745, 2020). "In addition, it has been demonstrated that liver-specific knockdown of nuclear receptor subfamily 2, group F, member 6 (NR2F6) alleviated obesity-associated hepatosteatosis and MCD diet-induced NASH through downregulating CD36 expression in mouse models." (PMID 37834101, 2023). "Together with the observations that Ad‐NR2F6‐injected mice exhibited more hepatic TG contents, these findings suggest that upregulation of NR2F6 represents a common feature of obesity‐related dyslipidemia and might be causally linked to the pathogenesis of NAFLD." (PMID 33173745, 2020). "Obesity‐induced upregulation of NR2F6 promotes the expression of CD36 in the liver, thereby facilitating fatty acid uptake and triglyceride retention, contributing to NAFLD and insulin resistance." (PMID 33173745, 2020). "However, expression levels of NR2F6 in while adipose tissue (WAT), brown adipose tissue (BAT), and skeletal muscle (SKM) were unaltered, suggesting that obesity‐associated upregulation of NR2F6 is liver‐specific." (PMID 33173745, 2020).
acute myeloid leukemia (3 papers, 2016 to 2023). Acute myeloid leukemia (AML) is a group of neoplasms arising from precursor cells committed to the myeloid cell-line differentiation. "In addition, NR2F6 expression is >4-fold in acute myeloid leukemia (AML) cells with growth ability than in cells without it; NR2F6 knockdown induces AML cell terminal differentiation and apoptosis." (PMID 27775588, 2016).
breast tumor (3 papers, 2015 to 2025). "NR2F6 silencing resulted in significantly reduced invasion of A375 into the perturbed human dermal fibroblasts, as well as in cancer associated fibroblasts isolated from breast tumor." (PMID 40847025, 2025). "scRNA-seq analysis of nonmetastatic primary breast tumors from patients subjected to a single dose of anti–PD-1 ICT revealed higher NR2F6 and FKBP10 expression in nonresponders [fig." (PMID 37406115, 2023).
experimental autoimmune encephalomyelitis (3 papers, 2014 to 2022). An autoimmune demyelinating disease of the central nervous system that is produced experimentally in animals by the injection of homogenized brain or spinal cord in Freund's adjuvant. "We have previously linked the orphan nuclear receptor NR2F6 (COUPTF-III, EAR2) to T cell function and defined it as an intracellular immune checkpoint in the context of cancer and as a suppressor of experimental autoimmune encephalomyelitis (EAE)." (PMID 36052079, 2022). "Indeed, in the experimental autoimmune encephalomyelitis (EAE) model, a significantly augmented disease progression of Nr2f6 knockout mice establishes a critical and non-redundant functional threshold mechanism of NR2F6 for repressing Th17 cell pathology both in vivo and in vitro." (PMID 24919548, 2014).
glioma (3 papers, 2021 to 2025). A benign or malignant brain and spinal cord tumor that arises from glial cells (astrocytes, oligodendrocytes, ependymal cells). "Functional enrichment analysis demonstrated that NR2F6 was associated with many biological processes that are related to glioma progression, such as angiogenesis, and with multiple immune-related functions." (PMID 37575237, 2023). "NR2F6 expression was significantly up-regulated in IDH-wildtype gliomas than IDH-mutated gliomas in TCGA as well as CGGA and in-house cohort." (PMID 37575237, 2023). "Since NR2F6 expression in glioma was strongly associated with malignancy, we inferred that NR2F6 may have important biologic functions in glioma." (PMID 37575237, 2023). "Therefore, we postulated that NR2F6 could be implicated in the immunosuppressive properties of glioma." (PMID 37575237, 2023). "To explore the expression pattern of NR2F6 in glioma, we first assessed NR2F6 expression in 663 RNA sequencing samples from the TCGA database, according to glioma grades." (PMID 37575237, 2023). "The GO functional analysis with DAVID was used to determine the biological role of NR2F6 in gliomas." (PMID 37575237, 2023). "Further investigation is required on the potential use of NR2F6 pathway inhibition in combination with multiple other immune checkpoint blockade for the treatment of glioma." (PMID 37575237, 2023). "First, we proved that the expression of NR2F6 was significantly upregulated in the higher malignant pathological type of gliomas." (PMID 37575237, 2023). "We found that NR2F6 was significantly related to high tumor aggressiveness and poor outcomes for glioma patients." (PMID 37575237, 2023). "NR2F6 expression was the highest in malignant cells and stromal cells in the microenvironment of gliomas." (PMID 37575237, 2023). "Subsequent analysis based on Gliomas single-cell sequencing datasets showed that NR2F6 was expressed in immune cells, tumor cells, and stromal cells." (PMID 37575237, 2023). "Taken together, these results indicated that NR2F6 expression was more prevalent in aggressive glioma." (PMID 37575237, 2023). "The higher expression of NR2F6 was significantly observed in high-grade versus low-grade glioma tissues." (PMID 37575237, 2023). "As shown, patients with glioma with lower NR2F6 expression exhibited significantly longer OS compared with patients with higher NR2F6 expression in both TCGA and CGGA cohorts." (PMID 37575237, 2023). "In this study, we comprehensively analyzed the expression pattern and related biological characteristics of the new immune checkpoint NR2F6 and its clinical significance in glioma." (PMID 37575237, 2023). "Our findings also showed that a high expression level of NR2F6 in glioma was relevant to a worse prognosis in both the TCGA and CGGA databases." (PMID 37575237, 2023). "This is the first study exploring the expression pattern, clinical value, and biological function of the immune checkpoint NR2F6 in glioma." (PMID 37575237, 2023). "The present study is the first to clinically, molecularly, and immunologically characterize NR2F6 expression in gliomas." (PMID 37575237, 2023). "Our results highlighted NR2F6, which positively interacts with other checkpoint proteins in glioma, as a promising candidate for immunotherapy." (PMID 37575237, 2023). "Through an in-depth analysis of the biological function of NR2F6 in glioma, we found that NR2F6 was involved in extracellular matrix organization, angiogenesis, cell adhesion, and other biological processes related to glioma progression." (PMID 37575237, 2023). "Higher expression of NR2F6 was observed in higher grades of glioma, highlighting the possible relationship between NR2F6 expression and a poorer prognosis." (PMID 37575237, 2023). "Our study systematically explored the clinical characteristics and biological functions of NR2F6 in gliomas." (PMID 37575237, 2023).
glioma (continued). "However, future studies would help confirming the crucial role of NR2F6 in gliomas by examining NR2F6 expression at protein levels." (PMID 37575237, 2023). "Moreover, NR2F6 was found to be significantly correlated with stromal and immune infiltration in gliomas." (PMID 37575237, 2023). "We also confirmed the NR2F6 gene expression feature in our own cohort of 60 glioma patients." (PMID 37575237, 2023). "We found that high expression of NR2F6 was closely related to high tumor aggressiveness and predicted a poor outcome, and that NR2F6 expression was involved in glioma immunosuppression, tumor invasion, and progression in the inflammatory microenvironment of glioma." (PMID 37575237, 2023). "Thus, we divided glioma patients into low and high-expression groups to evaluate NR2F6’s prognostic value." (PMID 37575237, 2023). "On the other hand, NR2F6 functions as an innate and adaptative immunity regulator: expressed in immune and stromal cells, promoting tumor escape from immune surveillance, resulting in poor outcomes for glioma patients." (PMID 37575237, 2023). "Our findings indicated that intracellular targeting of NR2F6 in both immune cells and tumor cells, as well as stromal cells, may represent a promising immunotherapeutic strategy for glioma." (PMID 37575237, 2023). "Nevertheless, a rigorous assessment of NR2F6 involvement in glioma patients has yet to be handled." (PMID 37575237, 2023). "In line with previous studies, these results indicate that NR2F6 might have dual pro-tumor activity in tumor cells and immune cells in the glioma microenvironment." (PMID 37575237, 2023). "Taken together, these findings revealed that NR2F6 might play an important immunosuppressive role in glioma through recruiting and promoting immunosuppressive cells to secrete immune-inhibitory cytokines, as well as regulating M2 transformation." (PMID 37575237, 2023). "Hence, the function of NR2F6 in glioma may be realized by the wide expression of NR2F6 in immune cells, glioma cells, and stromal cells." (PMID 37575237, 2023). "Studies have revealed that the upregulation of immune checkpoints such as PD-1, LAG-3, and B7-H3 in glioma aids tumor immune evasion, resulting in T cell dysfunction, which suggests that NR2F6 may promote glioma immune evasion through upregulation of immune checkpoint expression." (PMID 37575237, 2023). "Therefore, we set out to explore NR2F6 mRNA profiling in glioma through 1048 samples." (PMID 37575237, 2023). "Revealing the mechanism of NR2F6 in glioma may be the key to triumphing over this fatal disease." (PMID 37575237, 2023). "The top-ranking genes were related to the TRIP10, NR2F6, ACTN4, SBNO2, and TGFB1L1 genes (p < 0.05), and a link between ACTN4 and TGFB1L1 expression and tumorigenesis was shown in glioma samples." (PMID 34722629, 2021). "Thus, it can be inferred that the combination of NR2F6 blockade with other ICIs, such as PD-1, LAG-3, and B7-H3, may be an alternative treatment method for glioma patients." (PMID 37575237, 2023). "However, there has been no investigation of NR2F6 in glioma." (PMID 37575237, 2023).
Hepatic steatosis (3 papers, 2020 to 2025). Steatosis is a term used to denote lipid accumulation within hepatocytes. "Overexpression of Nr2f6 mice has been observed to induce hepatic steatosis in MASLD mouse model, whereas suppression of Nr2f6 was observed to improve IR and hepatic steatosis." (PMID 40211057, 2025). "Our findings might provide a new molecular basis for liver steatosis and identify NR2F6 as a therapeutic target for treatment of NAFLD/NASH and related liver diseases." (PMID 33173745, 2020). "Thus, we speculate that forced expression of NR2F6 could promote liver steatosis by specifically enhancing FFA uptake through CD36." (PMID 33173745, 2020). "Research shows that nuclear receptor subfamily 2 group F member 6 (NR2F6) promotes MASLD by activating CD36 gene expression, inducing TG retention, and providing a new molecular basis for hepatic steatosis." (PMID 39339660, 2024). "As a result, liver TG contents, plasma TG, and hepatic FFA levels were reduced in CD36‐depleted mice in the presence of NR2F6 overexpression, suggesting that NR2F6 cannot promote liver steatosis in the absence of CD36." (PMID 33173745, 2020). "Thus, our findings suggest that suppression of NR2F6 could alleviate symptoms of MCD diet‐induced NASH, including liver steatosis, inflammation, and injury." (PMID 33173745, 2020).
lung adenocarcinoma (3 papers, 2021 to 2023). A carcinoma that arises from the lung and is characterized by the presence of malignant glandular epithelial cells. "Previous research has shown that miR-142-3p suppresses cell proliferation, migration and invasion through inhibition of NR2F6 in lung adenocarcinoma and functions as a potential tumor suppressor in NSCLC." (PMID 37932766, 2023).
viral infection (3 papers, 2024). "Our work has identified NR2F6 as an important transcription factor involved in virus infection and virus-host interaction." (PMID 38829910, 2024). "We identified NR2F6 as one of the important host factors involved in the signaling network activated by viral infection through interaction with JAK/STAT and AP-1/c-Jun pathways." (PMID 38829910, 2024). "Here we show that NR2F6 is a critical factor involved in viral infection and the interaction between viruses and host cells." (PMID 38829910, 2024). "The result of ChIP-PCR showed that FB-tagged NR2F6 did not bind MAP3K5 without virus infection, and was recruited to MAP3K5 promoter region upon HSV-1 treatment." (PMID 38829910, 2024). "STAT3 knockdown enhanced NR2F6 expression, even in the cells without virus infection." (PMID 38829910, 2024).
autoimmune disease (2 papers, 2014 to 2025). A disorder resulting from loss of function or tissue destruction of an organ or multiple organs, arising from humoral or cellular immune responses of the individual to their own tissue constituents. "NR2F6 could potentially represent such a genetic risk factor for the development of autoimmune diseases through its regulation of pathogenic Th17 cells." (PMID 24919548, 2014). "Although our current preclinical knowledge strengthens this hypothesis, the direct causality of NR2F6 and incidence of human autoimmune disease remains yet to be demonstrated." (PMID 24919548, 2014). "Taken together, this NR2F6-centered pathway identified may very well offer new targets that are aimed at blocking the generation of pathogenic Th17 cells for the treatment of autoimmune diseases." (PMID 24919548, 2014).
Autoimmunity (2 papers, 2014 to 2025). The occurrence of an immune reaction against the organism's own cells or tissues. "This conveys an important message for Th17 subset selectivity and indicates that NR2F6 specifically counteracts the generation of the highly pathogenic Th17 cell type and decreases the risk of promoting autoimmunity." (PMID 24919548, 2014). "The role of NR2F6 in ECM differs from its role in autoimmunity." (PMID 40801595, 2025). "Overall, the multifaceted role of NR2F6 is to function as an intracellular immune checkpoint in adaptive and innate immunity, maintaining balanced immune activation to prevent excessive inflammation, which could otherwise lead to tissue damage or autoimmunity." (PMID 40801595, 2025). "NR2F6 serves as an antigen receptor signaling threshold-regulated barrier against autoimmunity where NR2F6 is part of a negative feedback loop that limits inflammatory tissue damage induced by weakly immunogenic antigens such as self-antigens." (PMID 24919548, 2014).
neuroblastoma (2 papers, 2011 to 2025). Neuroblastoma (NB) is the most common solid, extracranial childhood tumor. "This study aimed to investigate the expression level of NR2F6 in various tumors and its effect on neuroblastoma (NB)." (PMID 40424451, 2025).
non-small cell lung carcinoma (2 papers, 2022 to 2023). A group of at least three distinct histological types of lung cancer, including non-small cell squamous cell carcinoma, adenocarcinoma, and large cell carcinoma. "Furthermore, evaluating tumor-infiltrating lymphocytes from non-small cell lung cancer (NSCLC) patients’ biopsies provides substantial preclinical evidence that NR2F6 overexpression at the tumor niche produces effector T cells unable to mount a robust immune response against malignancy." (PMID 37575237, 2023).
sarcoma (2 papers, 2018 to 2023). A usually aggressive malignant neoplasm of the soft tissue or bone. "Nr2f6-deficient mice were significantly more resistant to development of MCA-induced sarcoma than wild-type mice and exhibited reduced tumor growth during challenge with a primary sarcoma cell line derived from MCA-treated wild-type mice." (PMID 29670099, 2018). "Moreover, anti-PD-L1 antibody treatment reduces the tumor growth of Nr2f6 knockout mice with sarcoma transplantation." (PMID 37373038, 2023). "In addition, Nr2f6 knockout mice are resistant to the generation of sarcoma induced by methylcholanthrene and sarcoma transplantation." (PMID 37373038, 2023). "Intratumoral immune cells in the MCA sarcoma model contained more abundant CD45+ and CD3+ lymphocytes in Nr2f6−/− versus wild-type Nr2f6+/+ mice." (PMID 29670099, 2018).
squamous cell carcinoma (2 papers, 2016 to 2023). A carcinoma arising from squamous epithelial cells. "The role of NR2F6 in the endometrial adenocarcinoma may be different compared to squamous cell carcinomas as of the oropharynx or cervix uteri." (PMID 36884115, 2023). "NR2F6 protein expression was markedly correlated with FIGO stage, squamous cell carcinoma (SCC) antigen, vital status, chemotherapy, tumor recurrence, and most importantly, LNM." (PMID 27775588, 2016).
alcoholic fatty liver disease (1 paper, 2020). Lipid infiltration of the hepatic parenchymal cells that is due to alcohol abuse. "NR2F6 (nuclear receptor subfamily 2, group F, member 6) is increased in the livers of obese mice and patients with non‐alcoholic fatty liver disease." (PMID 33173745, 2020).
cerebral malaria (1 paper, 2025). A sequestration of Plasmodium falciparum in the brain, which can cause coma and/or seizures. "Taken together, and in strict contrast to Nr2f6-knock-out mice, Nr2f6-proficient mice exhibited a heightened susceptibility to cerebral malaria pathogenesis." (PMID 40801595, 2025). "In light of the significant limitations in preventing, diagnosing and treating cerebral malaria, our finding that deleting the NR2F6 gene makes mice resistant to ECM by altering T cell migration enhances our understanding of the mechanisms that compromise the BBB integrity during ECM pathology." (PMID 40801595, 2025). "Along this line of argumentation, our investigation focuses on the role of nuclear orphan receptor NR2F6, an established immune checkpoint of the CD8+ T cell effector compartment, as a candidate driver of cerebral malaria pathology." (PMID 40801595, 2025). "We present evidence that NR2F6 deficiency renders mice more resistant to experimental cerebral malaria (ECM), confirming a causal and non-redundant role for NR2F6 in the progression of ECM disease." (PMID 40801595, 2025).
colon adenocarcinoma (1 paper, 2018). "In addition to the spontaneous MCA tumor model, we challenged wild-type and Nr2f6-deficient mice subcutaneously with the transplantable colon adenocarcinoma cell line MC38 and observed decreased tumor outgrowth and a significant survival benefit in Nr2f6−/− mice." (PMID 29670099, 2018).
COVID-19 (1 paper, 2023). A disease caused by infection with severe acute respiratory syndrome coronavirus 2. "For example, compared to activated STAT2 and KLF5 in mild/moderate goblet cells, SPDEF, ELF3, XBP1, and NR2F6 were found activated in patients with severe COVID-19." (PMID 37936693, 2023). "In goblet cells, STAT2 and KLF5 were highly activated and upregulated in many genes with mild/moderate COVID-19, such as ISGs (PARP14 and IFI44L), whereas ELF3, SBP1, NR2F6, and SPDEF were preferentially activated in severe COVID-19 to regulate the expression of their targets." (PMID 37936693, 2023). "Furthermore, NR2F6, SPDEF, and ELF3 were found to be activated in squamous cells in patients with severe COVID-19, and this activity was also shared with goblet cells." (PMID 37936693, 2023). "For example, RFX2 and RFX3 showed high activity in ciliated cells regardless of disease severity, while XBP1, NR2F6, SPDEF, and ELF3 were preferentially activated in goblet cells in patients with severe COVID-19, and KLF5 and STAT2 were coactivated in patients with mild/moderate COVID-19." (PMID 37936693, 2023).